SYCE1 (synaptonemal complex central element protein 1)
Description:
Major component of the transverse central element of synaptonemal complexes (SCS), formed between homologous chromosomes during meiotic prophase. Requires SYCP1 in order to be incorporated into the central element. May have a role in the synaptonemal complex assembly, stabilization and recombination.
Synonyms: CT76; C10orf94; bA108K14.6; POF12; SPGF15
Tractability: No criterion of Open Targets' tractability assessment is met for any kind of drug.
Gene: Protein-coding gene on chromosome 10 (133,553,901 to 133,569,835, reverse strand). Ensembl gene ENSG00000171772.
Subcellular location: Nucleus; Chromosome
Subcellular location (Human Protein Atlas): Nucleoplasm; Cytosol; Vesicles
Pathways (Reactome):
Reproduction: Meiotic synapsis
Gene Ontology:
Molecular function: protein binding
Biological process: homologous chromosome pairing at meiosis; homologous recombination; reciprocal meiotic recombination; synaptonemal complex assembly; synaptonemal complex organization
Cellular component: central element; chromosome; condensed nuclear chromosome; nucleus; synaptonemal complex
Genetic constraint (gnomAD): Loss-of-function variants: 38 observed, 55.32 expected, observed/expected ratio (o/e) 0.69, 90% interval 0.53 to 0.9. The upper end of that interval is the gene's LOEUF score, 0.9, which puts it in group 3 of 6, group 1 being the genes least tolerant of losing a copy. Missense variants: 399 observed, 421.18 expected, observed/expected ratio (o/e) 0.95, 90% interval 0.87 to 1.03. Synonymous variants: 163 observed, 159.41 expected, observed/expected ratio (o/e) 1.02, 90% interval 0.9 to 1.16.
Homologues: Orthologues: chimpanzee SYCE1 (98% identical), macaque SYCE1 (84% identical), pig SYCE1 (71% identical), dog SYCE1 (68% identical), rat Syce1 (60% identical), mouse Syce1 (60% identical), guinea pig SYCE1 (54% identical), tropical clawed frog syce1 (23% identical), zebrafish si:ch211-199g17.9 (18% identical). Paralogues in human: SYCE1L (37% identical).
Diseases named in the same sentence as SYCE1 in open-access papers:
SYCE1 is named in the same sentence as 19 diseases in open-access papers, as found by Europe PMC text mining. Sharing a sentence is not in itself a finding about the gene and the disease. The quoted sentences say what the papers report.
Infertility (7 papers, 2019 to 2025). "Here, we combine mouse genetics and cellular and biochemical studies to reveal a multivalent interaction mode between SYCE1 and SIX6OS1 that is disrupted by infertility-associated mutations of SYCE1." (PMID 32917591, 2020). "The mammalian SC has eight structural components, including SYCE1, the only central element protein with known causative mutations in human infertility." (PMID 32917591, 2020). "SYCE1’s infertility-associated mutations c.375-2A>G (NOA) and c.613C>T (POF) specifically disrupt the first and second interfaces, respectively." (PMID 32917591, 2020). "An important structural or functional role for SYCE1 C-termini is suggested by the identification of mutations associated with human infertility that generate truncated SYCE1 products." (PMID 30607510, 2019). "Interestingly, LoF mutations in SYCE1 are most frequent in the general population, and the associations between SYCE1 mutations and infertility are also well established." (PMID 35342360, 2022). "Finally, SYCE1 has been implicated in human infertility, with mutations giving rise to premature truncation or haploinsufficiency having been identified in cases of non-obstructive azoospermia and premature ovarian failure." (PMID 30607510, 2019). "So far, infertility-related mutations have been identified in four SC coding genes, including SYCP2, SYCP3, SYCE1, and C14ORF39." (PMID 35342360, 2022). "Four genes with the most observed LoF variants are SYCE1, C14ORF39, SYCP2, and SYCP3, corresponding to the four reported genes with infertility-related mutations." (PMID 35342360, 2022). "So far, infertility-related SC gene mutations are limited to four SC genes (SYCP2, SYCP3, C14ORF39, and SYCE1)." (PMID 35342360, 2022). "Mice harboring the SYCE1 POF mutation and a targeted deletion within SIX6OS1 (which disrupts the first interface) are infertile, with failure of SC assembly." (PMID 32917591, 2020). "Here, we report that SC assembly depends on multivalent interactions between CE components SYCE1 and SIX6OS1 that are disrupted by infertility-associated mutations of SYCE1." (PMID 32917591, 2020). "The SYCE1 gene encodes synaptonemal complex central element protein 1 (<−1.7-fold) and SYCE1L (<−1.6-fold), which are expressed in the synaptonemal complex of meiotic chromosomes and whose deficiency is linked to infertility in mice, both downregulated in LCFs." (PMID 41205594, 2025). "Thus, SIX6OS1 Δ10–21 leads to infertility with a phenotype of failed DSB repair and SC assembly, similar to the SYCE1 POF mutation and those reported for disruption of structural components of the CE." (PMID 32917591, 2020). "Furthermore, our analysis of SYCE1 infertility-associated mutations and a targeted internal deletion of SIX6OS1 revealed at least four possible conformations of SYCE1 and SYCE1-SIX6OS1 complexes." (PMID 32917591, 2020). "In common with other SC central element components, disruption of SYCE1 leads to complete infertility in mice owing to meiotic arrest in which there is failure of SC formation, with only weak discontinuous loading of SYCP1, and failure of double-strand break repair." (PMID 30607510, 2019). "Thus, it will be essential to evaluate how disruption of SYCE1 interactome may contribute to human infertility." (PMID 35342360, 2022). "However, as this truncation lies outside SYCE1’s structural core, the molecular mechanism that is disrupted, and thereby responsible for infertility, remains unknown." (PMID 32917591, 2020). "In addition, the team detected almost no production of SYCE1 protein in mice carrying the homozygous Syce1 mutation, suggesting that the mutation resulting in greatly reduced transcriptional activity of Syce1 is one of the key mechanisms leading to infertility." (PMID 37430352, 2023).
male infertility (2 papers, 2022). The inability of the male to effect fertilization of an ovum after a specified period of unprotected intercourse. "We identified that two novel CNVs within SYCE1 are associated with meiotic arrest and male infertility." (PMID 35718780, 2022). "Screening of male infertility‐related genes revealed a new homozygous mutation (c.689_690del; p.F230fs) in the exon region of the SYCE1 gene in the patient." (PMID 35023261, 2022). "Herein, we identified that two novel CNVs within SYCE1 caused meiotic arrest and male infertility." (PMID 35718780, 2022). "In summary, our research suggests that the novel homozygous mutation (c.689_690del; p.F230fs) altered the SYCE1 expression pattern and may have disturbed SC assembly, leading to male infertility and to a barrier to gamete formation." (PMID 35023261, 2022).
breast cancer (1 paper, 2025). A primary or metastatic malignant neoplasm involving the breast. "This study hypothesized that epigenetic processes, including DNA methylation, influence the expression of identified CG or testis-specific genes, such as SYCP1, ADAD1, SYCE1, PRSS54, DMRTC2, and TEX101, in breast cancer (BC), normal breast (NB), and chronic myelogenous leukemia (CML) cell lines." (PMID 41411337, 2025).
craniosynostosis (1 paper, 2025). Craniosynostosis is defined as the premature fusion of one or more cranial sutures leading to secondary distortion of skull shape resulting in skull deformities with a variable presentation. "The SCART1 and SYCE1 genes have no published research associated with craniosynostosis, bone homeostasis or any of the pathways investigated in the study." (PMID 40843495, 2025).
female infertility (1 paper, 2020). Diminished or absent ability of a female to achieve conception. "Thus, the SYCE1 POF mutation leads to male and female infertility with phenotypes of failed DSB repair, synapsis, and lastly SC assembly, similar to those previously observed upon disruption of structural components of the SC CE." (PMID 32917591, 2020).
leukemia (1 paper, 2025). A malignant (clonal) hematologic disorder, involving hematopoietic stem cells and characterized by the presence of primitive or atypical myeloid or lymphoid cells in the bone marrow and the blood. "The inverse methylation-expression correlation of SYCE1 in leukemia (ρ = −0.45) suggests epigenetic silencing, whereas TEX101’s positive correlation in BC implies alternative activation mechanisms." (PMID 41411337, 2025). "For leukemia patients, SYCE1 again displays relatively prolonged survival, while PRSS54 and TEX101 are linked to a more rapid decline." (PMID 41411337, 2025). "In leukemia, SYCE1 and TEX101 dominated pathway analysis, potentially regulating hematopoietic differentiation." (PMID 41411337, 2025). "In leukemia versus healthy blood donors, SYCP1, ADAD1, and SYCE1 were hypermethylated (~0.35 vs. ~ 0.17, ~ 0.84 vs. ~ 0.44, and ~0.45 vs. ~ 0.09, respectively), while PRSS54 was markedly hypomethylated (~0.08 vs. ~ 0.86)." (PMID 41411337, 2025). "In leukemia versus healthy donors, GO enrichment revealed that TEX101, ADAD1, PRSS54, and SYCE1 were the most enriched genes, whereas SYCP1 and DMRTC2 exhibited minimal enrichment." (PMID 41411337, 2025). "Methylation-expression correlations were stronger in tumors, with SYCE1 and DMRTC2 showing inverse relationships in leukemia." (PMID 41411337, 2025). "We comprehensively analyzed differential methylation, survival analysis (Kaplan-Meier), correlation (Spearman’s), and pathway enrichment analysis (GO/KEGG) of CG genes (SYCP1, ADAD1, SYCE1, PRSS54, DMRTC2, and TEX101) in BC and leukemia." (PMID 41411337, 2025). "In leukemia samples, SYCE1 and DMRTC2 demonstrated stronger negative correlations, implying that hypermethylation may suppress their expression." (PMID 41411337, 2025).
premature ovarian failure (1 paper, 2024). "SYCE1 belongs to disease-related genes in The Human Protein Atlas, and diseases associated with SYCE1 include spermatogenic failure and premature ovarian failure." (PMID 37817005, 2024).
Primary amenorrhea (1 paper, 2023). "Homozygous SYCE1 mutations with obvious family inheritance may lead to primary amenorrhea or secondary amenorrhea." (PMID 37430352, 2023).
Turner syndrome (1 paper, 2017). Turner syndrome is a chromosomal disorder associated with the complete or partial absence of an X chromosome. "When this is the case, the underlying pathogenetic mechanism of follicle depletion are heterogeneous ranging from genetic (Turner’s syndrome, mutations in the genes FMR-1, BMP-15, Foxl2, and recently identified MCM9, SYCE1, STAG3) to auto-immune and iatrogenic causes." (PMID 29176793, 2017).
cancer (3 papers, 2014 to 2025). A tumor composed of atypical neoplastic, often pleomorphic cells that invade other tissues. "SYCP1 and SYCE1 maintained modest inverse correlations, whereas PRSS54 and TEX101 showed no significant methylation-expression relationship, highlighting the cancer-specific nature of these epigenetic interactions." (PMID 41411337, 2025). "Nonetheless, many genes that have been described as targets of Dnmt3b in the mouse, including MAEL, SYCE1, and SYCP1, are aberrantly expressed in human cancers and are listed as cancer testes genes." (PMID 25198254, 2014).
tumor (1 paper, 2025). "In contrast, SYCE1 and PRSS54 displayed reduced methylation in BC tumor (~0.26 vs. ~ 0.52 and ~0.20 vs. ~ 0.37, respectively)." (PMID 41411337, 2025). "For tumor stage, SYCP1 and ADAD1 showed negligible positive correlations (ρ = 0.02, 0.08, respectively), while SYCE1, PRSS54 and DMRTC2 exhibited slight negative correlations." (PMID 41411337, 2025).
SYCE1 also shares sentences with these, for which no sentence is quoted: Azoospermia (3 papers); autism (1); chronic myelogenous leukemia (1); colon cancer (1); ovarian insufficiency (1); Sertoli Cell-Only Syndrome (1); spermatogenic failure (1); spermatogenic failure 15 (1).